GNL3L (G protein nucleolar 3 like)
Diseases named in the same sentence as GNL3L in open-access papers (continued):
Sharing a sentence is not in itself a finding about the gene and the disease.
tumor (8 papers, 2017 to 2025). "The association of GNL3L with tumor mutational burden (TMB), tumor microsatellite instability (MSI), mismatch repair (MMR) genes, and immune cells was then analyzed." (PMID 36230520, 2022). "According to the TCGA EC datasets, the expression of GNL3L in EC tumor tissues was greater than that in normal esophageal tissues." (PMID 40856423, 2025). "The link between GNL3L and tumor-infiltrating immune cells was studied in 33 malignancies in this study." (PMID 36230520, 2022). "Following the discovery of GNL3L’s predictive usefulness, the researchers investigated the link between GNL3L and tumor-infiltrating immune cells in 33 malignancies." (PMID 36230520, 2022). "GNL3L has been discovered as a factor involved in the maintenance of the tumorigenic properties of tumor-initiating cells." (PMID 34733320, 2021). "It has been shown that overexpression of GNL3L drives the fraction of genetically defined tumour cells that exhibit markers and tumourigenic properties of tumour initiating cells of enhanced radio-resistance and propensity to metastasize." (PMID 32345361, 2020). "Recently, GNL3L has been identified as one of the factors responsible for the maintenance of the tumorigenic properties of tumor-initiating cells, and it promotes NF-κB-mediated cell survival via the upregulation of antiapoptosis-related genes." (PMID 32422901, 2020). "We further validated miR-4454 and GNL3L expression levels in the excised tumor tissue from each group." (PMID 32422901, 2020). "In this study, we demonstrated that the loss of miR-4454 expression in a resistant clone prominently promoted tumor initiation, metastatic outgrowth, and resistant status through the GNL3L/NFκB signaling axis against anticancer drug therapy." (PMID 32422901, 2020). "GNL3L promotes S phase progress and tumor cell proliferation by regulating the Rb‐E2F1 pathway." (PMID 40856423, 2025). "The schematic diagram of the present study shows that chemoresistance-associated silencing of miR-4454 promotes CRC aggression, reverted through the overexpression of miR-4454 by targeting GNL3L (tumor initiation or maintenance-related gene) and the NFκB pathway." (PMID 32422901, 2020). "The results showed that the silenced GNL3L reduced the tumor volume significantly in the LoVo cell group compared with that of the control group, and we further confirmed GNL3L expression using Western blotting and immunohistochemistry and NF-κB expression using IHC." (PMID 32422901, 2020). "In addition, the expression of GNL3L and survival probability were related to tumor grade." (PMID 40856423, 2025). "Moreover, GNL3L overexpression increases tumor cell proliferation." (PMID 40856423, 2025). "Moreover, GNL3L may enhance NF-κB-regulated tumor cell viability via the upregulation of antiapoptosis-related genes." (PMID 34733320, 2021). "In view of the observation that methylated CpG in the gene body is accompanied by gene overexpression, our estimate on GNL3L is consistent with its role in tumour, supporting that some of the age-dependent methylation changes could be implicated in carcinogenesis." (PMID 32345361, 2020). "However, the molecular mechanisms of GNL3L tumor initiation and resistant state are largely unknown." (PMID 32422901, 2020). "Then, in order to explore its immune value, the correlation of GNL3L with TMB, MSI, MMR, and various immune cells was analyzed and we made an analysis of the immune tumor microenvironment." (PMID 36230520, 2022).
GNL3L also shares sentences with these, for which no sentence is quoted: melanoma (2 papers); bladder urothelial carcinoma (1); breast invasive carcinoma (1); cholangiocarcinoma (1); colon adenocarcinoma (1); diffuse large B-cell lymphoma (1); endometrial carcinoma (1); glioma of the brain (1); head and neck squamous cell carcinoma (1); liver cancer (1); lung adenocarcinoma (1); lung carcinoma (1); lung squamous cell carcinoma (1); lymphoma (1); neuroblastoma (1); ovarian carcinoma (1); pancreatic cancer (1); rectal adenocarcinoma (1); renal carcinoma (1); renal papillary cell carcinoma (1); skin cancer (1); skin melanoma (1); stomach cancer (1); testis cancer (1); thyroid cancer (1); uterine carcinosarcoma (1).